GANC (glucosidase alpha, neutral C)
Description:
Has alpha-glucosidase activity.
Tractability: Small molecule: it belongs to a druggable protein family. PROTAC: ubiquitination databases record sites on it; its protein half-life has been measured; a small molecule that binds it is known.
Target class: Enzyme; Hydrolase
Gene: Protein-coding gene on chromosome 15 (42,273,201 to 42,353,666, forward strand). Ensembl gene ENSG00000214013.
Subcellular location (Human Protein Atlas): Cytosol
Gene Ontology:
Molecular function: alpha-1,4-glucosidase activity; alpha-glucosidase activity; carbohydrate binding; hydrolase activity, hydrolyzing O-glycosyl compounds
Biological process: carbohydrate metabolic process
Genetic constraint (gnomAD): Loss-of-function variants: 65 observed, 81.51 expected, observed/expected ratio (o/e) 0.8, 90% interval 0.65 to 0.98. The upper end of that interval is the gene's LOEUF score, 0.98, which puts it in group 4 of 6, group 1 being the genes least tolerant of losing a copy. Missense variants: 875 observed, 877.27 expected, observed/expected ratio (o/e) 1, 90% interval 0.94 to 1.05. Synonymous variants: 293 observed, 307.05 expected, observed/expected ratio (o/e) 0.95, 90% interval 0.87 to 1.05.
Homologues: Orthologues: chimpanzee GANC (99% identical), macaque GANC (97% identical), pig GANC (89% identical), rabbit GANC (88% identical), guinea pig GANC (85% identical), dog GANC (85% identical), mouse Ganc (84% identical), rat Ganc (83% identical), tropical clawed frog ganc (59% identical), zebrafish ganc (52% identical), Drosophila melanogaster GCS2alpha (41% identical), Caenorhabditis elegans aagr-4 (40% identical), and 2 more. Paralogues in human: GANAB (50% identical), GAA (27% identical), SI (26% identical), MGAM (26% identical), MGAM2 (25% identical), MYORG (12% identical).
Diseases named in the same sentence as GANC in open-access papers:
GANC is named in the same sentence as 7 diseases in open-access papers, as found by Europe PMC text mining. Sharing a sentence is not in itself a finding about the gene and the disease. The quoted sentences say what the papers report.
cardiac hypertrophy (1 paper, 2025). "Further investigation into the roles of miR-34a, miR-351, and miR-490*, alongside validated genes such as HTR2A, SGPP1, ITGA7, and GANC is essential to elucidate their contributions to early-onset cardiac hypertrophy." (PMID 41468376, 2025).
diabetes (1 paper, 2022). "GANC encodes a member of the glycosyl family, which is a key enzyme in the metabolism of glycogen and is associated with susceptibility to diabetes." (PMID 34979897, 2022).
liver cirrhosis (1 paper, 2019). "Mutations of GANC gene occurred in 21% patients and were found to be associated with liver cirrhosis (p-value = 0.037)." (PMID 31429776, 2019).
peripheral nerve injury (1 paper, 2022). Injury to a peripheral nerve. "Consistent with the expression changes of MOGS, the expressions of many metabolism-associated genes, including DDOST, TUSC3, STT3A, STT3B, RPN1, MAGT1, and GANC, were elevated after peripheral nerve injury." (PMID 35575968, 2022).
viral infection (1 paper, 2025). "The variant frequency of the GANC gene in H7N9-infected patients is higher than in the healthy population, thus, we hypothesize that the GANC variants should promote viral infection; however, these variants impair their ability to facilitate the replication of IAV." (PMID 40263249, 2025).
infection (1 paper, 2025). The state of being infected such as from the introduction of a foreign agent such as serum, vaccine, antigenic substance or organism. "We first identified the association of the GANC gene with human H7N9 infections through WGS." (PMID 40263249, 2025). "Our investigation has unveiled significant insights into the role of glucosidase alpha, neutral C (GANC) gene in human H7N9 infections." (PMID 40263249, 2025). "We discovered a mechanism by which GANC knockdown limits the infection of the H7N9 virus by targeting HA degradation." (PMID 40263249, 2025). "Indeed, GANC overexpression increased HA protein levels at 24 h, 36 h, and 48 h post-infection, while GANC siRNA or GANC+/− cells reduced HA protein levels in A549 cells infected with H7N9 virus." (PMID 40263249, 2025). "In addition, we observed a significant reduction in virus titer following the H9N2 virus or H1N1-PR8 virus infection, post-siRNA transfection, or in GANC+/− cells." (PMID 40263249, 2025). "The results showed that the mRNA and protein levels of GANC were slightly lower in H7N9 virus-infected cells at 24 h, 36 h, and 48 h post-infection compared to control group." (PMID 40263249, 2025). "Similarly, in vivo experiments demonstrated that inhibited mRNA and protein levels of GANC in H7N9 virus-infected mice compared to phosphate-buffered saline (PBS) treated-control mice on days 1 and 4 post-infection." (PMID 40263249, 2025). "Co-IP assays confirmed the interaction between GANC and endogenous and exogenous PSMD1/PSMD2 in the non-infected group and upon H7N9 infection." (PMID 40263249, 2025).
GANC also shares sentences with these, for which no sentence is quoted: tumor (1 paper).